SPATA33 (spermatogenesis associated 33)
Description:
Plays an important role in sperm motility and male fertility (By similarity). Required for sperm midpiece flexibility and for the localization of sperm calcineurin to the mitochondria (By similarity). Promotes mitophagy as well as acts as an autophagy mediator in male germline cells (By similarity). Links damaged mitochondria to autophagosomes via its binding to the outer mitochondrial membrane protein VDAC2, as well as to key autophagy machinery component ATG16L1 (By similarity).
Synonyms: C16orf55; FLJ31606
Tractability: No criterion of Open Targets' tractability assessment is met for any kind of drug.
Gene: Protein-coding gene on chromosome 16 (89,657,740 to 89,671,272, forward strand). Ensembl gene ENSG00000167523.
Subcellular location: Cytoplasm, cytosol; Nucleus; Cytoplasm; Mitochondrion
Subcellular location (Human Protein Atlas): Nucleoplasm; Vesicles
Gene Ontology:
Molecular function: protein binding; protein-containing complex binding
Biological process: mitophagy
Cellular component: cytoplasm; mitochondrion; nucleus; sperm midpiece; sperm mitochondrial sheath; cytosol
Genetic constraint (gnomAD): Loss-of-function variants: 12 observed, 10.44 expected, observed/expected ratio (o/e) 1.15, 90% interval 0.73 to 1.77. The upper end of that interval is the gene's LOEUF score, 1.77, which puts it in group 6 of 6, group 1 being the genes least tolerant of losing a copy. Missense variants: 241 observed, 184.05 expected, observed/expected ratio (o/e) 1.31, 90% interval 1.18 to 1.46. Synonymous variants: 96 observed, 75.89 expected, observed/expected ratio (o/e) 1.26, 90% interval 1.07 to 1.5.
Homologues: Orthologues: chimpanzee SPATA33 (99% identical), macaque SPATA33 (89% identical), guinea pig SPATA33 (65% identical).
Diseases named in the same sentence as SPATA33 in open-access papers:
SPATA33 is named in the same sentence as 13 diseases in open-access papers, as found by Europe PMC text mining. Sharing a sentence is not in itself a finding about the gene and the disease. The quoted sentences say what the papers report.
melanoma (4 papers, 2022 to 2024). A malignant, usually aggressive tumor composed of atypical, neoplastic melanocytes. "SPATA33 has long been associated with facial pigmentation, cutaneous squamous cell carcinoma, and melanoma." (PMID 36035146, 2022). "Similarly, the 3′aTWAS gene spermatogenesis-associated 33 (SPATA33), which encodes a mammalian germline mitophagy receptor, is simultaneously related to the risk of melanoma, basal cell carcinoma, and skin cancer." (PMID 38409266, 2024).
Infertility (3 papers, 2021 to 2024). "The deletion of Spata33 was also reported to cause abnormalities in sperm formation with sperm midpiece defects and infertility." (PMID 37956172, 2023). "Although it remains to be determined if inhibiting the interaction of sperm calcineurin and SPATA33 could cause infertility in humans, it could be one option of a combinational contraceptive strategy that targets multiple steps of fertilization." (PMID 34446558, 2021). "The ultrastructure and formation of the mitochondrial sheath have been described in previous studies, and knockout of several genes (e.g., ARMC12, SPATA33, and VDAC3) is known to cause abnormal mitochondrial sheath formation and subsequent infertility." (PMID 38443933, 2024).
skin cancer (3 papers, 2018 to 2024). "Multiple SNPs were identified in 16q24 (DEF8 and SPATA33 locus) that are associated with pigmentation traits, tanning response, and skin cancer risk." (PMID 35449187, 2022). "17: 37,827,375–38,134,431; hg19); skin pigmentation and skin cancer, which are clustered about the SPATA33–URAHP region (Chr." (PMID 30518762, 2018).
male idiopathic infertility (2 papers, 2013 to 2021). "Further studies on the functions of the novel gene Spata33 in spermatogenesis will provide insight into male idiopathic infertility." (PMID 23844118, 2013). "Revealing how SPATA33 and sperm calcineurin regulate midpiece flexibility could shed light on understanding male infertility and may lead to the development of nonhormonal male contraceptives." (PMID 34446558, 2021).
squamous cell carcinoma (1 paper, 2022). A carcinoma arising from squamous epithelial cells. "The novel freckles-associated variant rs35415928 in SPATA33 serves as a strong eQTL for several genes in both skin tissue (sun-exposed and no-sun-exposed) and fibroblasts, showing the strongest association with DBNDD1, a gene involved in tanning ability and squamous cell carcinoma." (PMID 36035146, 2022).
tuberculosis (1 paper, 2022). A chronic, recurrent infection caused by the bacterium Mycobacterium tuberculosis. "Lastly, the region on BTA 18 was reported as a candidate region for tuberculosis resistance, milk, and fertility traits including spermatogenesis-associated proteins 33 and 2L (SPATA33 and SPATA2L) in the extended regions of 250 kb." (PMID 36712857, 2022).
SPATA33 also shares sentences with these, for which no sentence is quoted: basal cell carcinoma (1 paper); cutaneous melanoma (1); cutaneous squamous cell carcinoma (1); Fanconi anemia (1); non-melanoma skin carcinoma (1); oculocutaneous albinism (1); Pigmentary retinopathy (1).